FGF23 (fibroblast growth factor 23)
Diseases named in the same sentence as FGF23 in open-access papers (continued):
Sharing a sentence is not in itself a finding about the gene and the disease.
hypophosphatemia (continued). "Previous studies have shown that FGF-23 is involved in the development of hypophosphatemia and bone diseases, these results suggest that FGF23 has an important role in bone metabolism." (PMID 32984251, 2020). "Laboratory analysis revealed hypophosphatemia and elevated alkaline phosphatase, parathyroid hormone, and FGF-23." (PMID 31963334, 2020). "Laboratory evaluation was notable for persistent hypophosphatemia due to urinary phosphate wasting, low to low-normal 1,25-dihydroxyvitamin D, elevated alkaline phosphatase and elevated fibroblast growth factor 23 (FGF23)." (PMID 32655879, 2020). "A different study observed higher FGF23 levels in COPD patients with hypophosphatemia as compared to COPD patients with normal phosphate levels." (PMID 31075857, 2019). "When FGF23 was first described as the causative agent of ADHR, the authors commented on the similarities between ADHR and other diseases of inherited hypophosphatemia, including XLH." (PMID 30808384, 2019). "Burosumab is a fully human monoclonal antibody targeting FGF23 that is under development for the treatment of FGF23‐related hypophosphatemia including XLH." (PMID 30828689, 2019). "Increased FGF23 affects calcitriol synthesis and degradation, thus hindering its ability to counterbalance hypophosphatemia." (PMID 30808384, 2019). "Elevated FGF23 has also been observed in many other diseases of hypophosphatemia, and a range of animal models have been developed to study these diseases, yet the role of FGF23 in the pathophysiology of XLH is incompletely understood." (PMID 30808384, 2019). "Phosphate is freely filtered at the glomerulus and then reabsorbed, but proximal tubular reabsorption is inhibited by both PTH and FGF‐23, resulting in hypophosphatemia." (PMID 31687644, 2019). "Autosomal dominant and autosomal recessive forms of FGF23‐mediated hypophosphatemias show a similar pathophysiology, despite a variety of different underlying genetic causes." (PMID 31485552, 2019). "X-linked hypophosphatemia (XLH) is characterized by excess fibroblast growth factor 23 (FGF23), hypophosphatemia, skeletal abnormalities, and growth impairment." (PMID 31259293, 2019). "Transgenic mice overexpressing FGF23 have decreased urinary phosphate reabsorption, hypophosphatemia, low serum 1,25-dihydroxyvitamin D [1,25(OH)2D] levels, and hyperparathyroidism." (PMID 30736285, 2019). "Since IGF-1 is associated with enhanced bone mineralization and upregulation of FGF23 it is assumed that in case IGF-1 is contributing to the regulation of the P homeostasis it would be downregulated in states of hypophosphatemia." (PMID 31329617, 2019). "X-linked hypophosphatemic rickets (XLH) is the first cause of inherited hypophosphatemia and is caused by mutation in the PHEX gene, resulting in excessive expression of the phosphaturic factor FGF23." (PMID 31151476, 2019). "The degree of FGF23 elevationmay be useful in differentiating inherited or acquired hypophosphatemia from TIO." (PMID 31850815, 2019). "Patients with FGF-23-mediated hypophosphatemia, especially children, need to be referred to a metabolic bone specialist with experience in phosphate wasting disorders." (PMID 31196103, 2019). "TIO was defined by hypophosphatemia, elevated serum FGF‐23, low 1,25(OH)2D, and decreased percentage of tubular reabsorption of phosphate (%TRP)." (PMID 31372587, 2019). "FGF23‐mediated forms of hypophosphatemia are characterized by phosphaturia and low or low‐normal calcitriol concentrations, and unlike nutritional rickets, these cannot be cured with nutritional vitamin D supplementation." (PMID 31485552, 2019). "Disturbed regulation of the physiological responses of calcitriol to hypophosphatemia, in addition to the downregulation of the renal phosphate transporter channels, thus contribute to hypophosphatemia in diseases of excess FGF23 such as XLH." (PMID 30808384, 2019).
hypophosphatemia (continued). "Iron deficiency triggers the accumulation of uncleaved FGF23 in ADHR patients, leading to the manifestation of the hypophosphatemia and rickets/osteomalacia." (PMID 30972027, 2019). "Phosphate-independent effects of FGF23 can therefore be identified by comparing the pathophysiology of patients with HHRH to those with FGF23-high hypophosphatemias." (PMID 30808384, 2019). "The majority of patients included in the selected studies had symptomatic osteomalacia with hypophosphatemia and evidence of increased serum levels of FGF23." (PMID 31861469, 2019). "It has been suggested that the persistence of high serum levels of the phosphaturic hormone FGF23 has an important role in the pathogenesis of post-transplantation hypophosphatemia." (PMID 29874852, 2018). "Mild hypophosphatemia as a result of FGF-23-mediated hyperphosphaturia was evident in two-thirds of the patients." (PMID 29599748, 2018). "This diagnosis was made after this patient underwent a somatostatin scan, despite a normal serum level of FGF23, because he suffered from progressive hypophosphatemia." (PMID 30180816, 2018). "Hypophosphatemia with high FGF23 in this disease again suggests the involvement of signals from FGF receptor in FGF23 production." (PMID 29515522, 2018). "As a result, high levels of PTH and FGF-23 result in significant urinary phosphorus losses and hypophosphatemia." (PMID 30109232, 2018). "Ideally, FGF23 values in our patients with hypophosphatemia should be compared to FGF23 values in persons with FGF23-independent hypophosphatemia." (PMID 30180816, 2018). "A mutation in the FAM20C gene is reported to cause down-regulation in Dmp1 mRNA expression and up-regulation of the fibroblast growth factor 23 (FGF23) mRNA expression, which results in FGF23-related hypophosphatemia in RS." (PMID 29751744, 2018). "This patient had a normal serum FGF23 level of 110 RU/ml but progressive hypophosphatemia which required increasing doses of phosphate replacement." (PMID 30180816, 2018). "We observed that the cKO mice developed skeletal defects and hypophosphatemia, along with altered levels of DMP1, OPN, bone sialoprotein (BSP) and FGF23 in the Fam20C-deficient bone." (PMID 28620244, 2017). "DMP1 knockout mice have displayed increased serum levels of FGF23, hypophosphatemia, skeletal and dental anomalies and osteomalacia." (PMID 29280738, 2017). "Additional assessments of the patient revealed not only hypocalcemia, but also hypophosphatemia, hypomagnesemia, osteomalacia, and a high concentration of fibroblast growth factor 23 (314 pg/mL)." (PMID 28953654, 2017). "Laboratory testing showed hypophosphatemia due to renal phosphate wasting and high levels of serum FGF23." (PMID 28193220, 2017). "Because it has been reported that SFO can lead to hypophosphatemia via elevation of FGF23, we discontinued the SFO." (PMID 28953654, 2017). "Increased FGF23 leads to renal phosphate wasting, hypophosphatemia and deterioration of bone mineralization." (PMID 29280738, 2017). "Recently, it has been strongly recommended that patients with osteomalacia with hypophosphatemia have serum FGF23 level checked." (PMID 28953654, 2017). "Tumor-induced osteomalacia (TIO) is a rare paraneoplastic syndrome characterized by severe hypophosphatemia and osteomalacia related to abnormal tumor production of fibroblast growth factor 23 (FGF23)." (PMID 28934935, 2017). "It has been suggested that PHEX acts directly or indirectly upstream of FGF23 in bone, because the loss of PHEX leads an increase of FGF23 and hypophosphatemia." (PMID 29040309, 2017). "Mutations that alter the arginine (R) residue at the position 176 or 179 would render the protein resistant to proteolytic cleavage and lead to increased serum levels of FGF23 and its activity, resulting in hypophosphatemia." (PMID 29280738, 2017).
hypophosphatemia (continued). "The overproduction of FGF23 by phosphaturic mesenchymal tumor results in an elevation of renal phosphorus wasting and impairment of intestinal phosphorus absorption, leading to hypophosphatemia and osteomalacia." (PMID 28193220, 2017). "Saccharated ferric oxide has been shown to lead to elevation of fibroblast growth factor 23, hypophosphatemia, and, consequently, osteomalacia." (PMID 28953654, 2017). "It is well known that Hyp mice are characterized by hypophosphatemia, hypocalcemia, impaired bone mineralization, and increased serum Fgf23." (PMID 27035636, 2016). "In FGF23-dependent HR, the physiological increase in serum 1,25(OH)2D in response to hypophosphatemia is blunted, and the result is a serum level of 1,25(OH)2D that is low, or inappropriately normal for the degree of hypophosphatemia." (PMID 26543054, 2016). "Hyp mice, a murine homologue of XLH, are characterized by hypophosphatemia, inappropriately low serum vitamin D levels, increased serum fibroblast growth factor-23 (Fgf23), and osteomalacia." (PMID 27035636, 2016). "Both XLH patients and Hyp mice are characterized by hypophosphatemia, impaired bone mineralization, inappropriately low serum vitamin D hormone (1,25(OH)2D3), and increased circulating intact fibroblast growth factor-23 (FGF23)." (PMID 27035636, 2016). "Although Fgf23 is known to be responsible for hypophosphatemia and reduced vitamin D hormone levels in Hyp mice, its putative role as an auto-/paracrine osteomalacia-causing factor has not been explored." (PMID 27035636, 2016). "Ablation of the Fam20c gene in conditional knockout mice affects tooth and bone development by downregulation of SIBLING family of proteins such as DMP1 and DSPP and by increasing FGF23 in serum and promoting phosphate excretion and hypophosphatemia." (PMID 27187611, 2016). "Elevated levels of serum phosphate increase the expression of FGF23 thereby decreasing the reabsorption of phosphate in the renal proximal tubule, while hypophosphatemia normally down regulates the expression of FGF23." (PMID 26543054, 2016). "FGF23 dependent HR is caused by mutations in genes involved in the FGF23 bone–kidney-axis, with levels of intact FGF23 (iFGF23) being elevated or inappropriately normal in the setting of hypophosphatemia when suppressed FGF23 is to be expected." (PMID 26543054, 2016). "Hyp mice exhibit phosphaturia and hypophosphatemia due to excess circulating FGF23 and this hypophosphatemic effect is completely rescued when the fgf23 gene is deleted in Hyp/fgf23-/- mice." (PMID 26588476, 2015). "In WT mice, FGF23 induced hypophosphatemia and suppressed expression of the renal Na/Pi cotransporters, Npt2a and Npt2c." (PMID 26588476, 2015). "We have shown that ERK1/2 signaling blockade suppresses renal egr-1 gene expression and prevents FGF23-induced hypophosphatemia and 1,25-dihydroxyvitamin D (1,25(OH)2D) suppression in mice." (PMID 26588476, 2015). "Both of ectopic (hepatic) overexpression and osteoblast/osteocyte-specific overexpression of the Fgf23 transgene result in lower bone mineral density of the femur with hypophosphatemia and high serum levels of PTH." (PMID 25873956, 2015). "In Hyp/egr-1-/- mice which have chronically high circulating FGF23 concentrations, deletion of the egr-1 gene improves hypophosphatemia by 50% when compared to Hyp mice." (PMID 26588476, 2015). "Mice transgenic for human FGF23 exhibit increased phosphate excretion, hypophosphatemia, hyperparathyroidism, and bone mineralization defects." (PMID 26491212, 2015). "A complete lack of DMP1 in the context of normal renal function results in increased circulating FGF23, hypophosphatemia, low 1,25(OH)2vitamin D levels and diffuse osteomalacia/rickets." (PMID 25774916, 2015). "A recent study reported that FAM20C supresses FGF23 production by enhancing DMP1 expression and that inactivation mutations in FAM20C cause FGF23 related hypophosphatemia by decreasing transcription of DMP1." (PMID 25928877, 2015).
hypophosphatemia (continued). "Measurement of FGF23 for hypophosphatemic patients is therefore useful for the diagnosis of FGF23-dependent hypophosphatemia." (PMID 25861491, 2015). "After resection of the tumor, hypophosphatemia and the increased levels of FGF-23 normalized within a few days." (PMID 25221676, 2014). "We confirmed hypophosphatemia and elevated levels of serum FGF23 in Hyp mice at this age in both male hemizygotes and female heterozygotes." (PMID 24710520, 2014). "The inactivation of PHEX/Phex or DMP1/Dmp1 has been shown to result in the increased expression of FGF23/Fgf23, leading to increased renal Pi wasting and hypophosphatemia in both humans and mice." (PMID 24710520, 2014). "In response to hypophosphatemia, FGF23 secretion is adequately suppressed, and 1,25-diOH-vitamin D production and absorption of calcium through the gut and urinary calcium excretion are consequently enhanced." (PMID 24550322, 2014). "More importantly, both the elevated serum FGF23 and hypophosphatemia in Hyp mice were significantly improved in compound Hyp;Fgfr1Dmp1-cKO-null mice." (PMID 25089825, 2014). "More research is needed to determine the relationships between PTH, FGF-23, and hypophosphatemia with TMV bone parameters, and to identify possible therapeutic targets." (PMID 24605319, 2014). "In addition, activating mutations in human FGFR1 cause osteoglophonic dysplasia (OMIM #166250) associated with increased levels of FGF23 and hypophosphatemia, which also suggests that activated FGF/FGFR signaling may play a role in regulation of Fgf23 expression." (PMID 24710520, 2014). "Laboratory examination showed hypophosphatemia, hyperphosphaturia, normocalcemia, an elevated serum alkaline phosphatase level, and an elevated serum FGF23 level." (PMID 25181387, 2014). "FGF23 has been proposed to be involved in the occurrence of hypophosphatemia after iron administration." (PMID 25478250, 2014). "Intriguingly, pharmacological activation of FGFR1 by R1MAb1 injection did not result in an apparent defect in bone mineral density in db/db mice despite the ability of R1MAb1 to induce FGF23 production and hypophosphatemia." (PMID 23451204, 2013). "Continuous production of recombinant FGF23 from implanted cell line was also shown to induce marked hypophosphatemia (∼50% of normal) and osteomalacia in nude mice at day 45 after the implantation." (PMID 23451204, 2013). "The mechanistic basis for hypophosphatemia in OGD is unclear, although one individual with hypophosphatemia has been found to have elevated circulating FGF23 levels." (PMID 23451204, 2013). "FGFRs also regulate skeletal FGF23 secretion; ectopic FGFR activation is implicated in genetic conditions associated with FGF23 overproduction and hypophosphatemia." (PMID 23451204, 2013). "In contrast, excessive FGF23 production or activity results in hypophosphatemia, osteomalacia, and rickets." (PMID 22590632, 2012). "Impaired renal excretion of FGF23 was proved to be the mechanism of renal osteodystrophy and post-transplant hypophosphatemia." (PMID 22551310, 2012). "Elevation of the FGF23 plasma level is known to lead to renal phosphate-wasting and hypophosphatemia." (PMID 22615579, 2012). "Our data show that both transgenes fully rescue the skeletal abnormalities of Dmp1 null mice as well as normalizing elevated circulating FGF-23 levels and hypophosphatemia." (PMID 20734454, 2011). "Renal 1,25(OH)2D production in humans is normally enhanced by PTH, hypocalcaemia, and hypophosphatemia and inhibited by 1,25(OH)2D and fibroblast growth factor 23 (FGF23)." (PMID 21731765, 2011). "Biochemistries were consistent with hypophosphatemia owing to renal phosphate wasting; markers of bone turnover and serum fibroblast growth factor 23 (FGF-23) levels were increased significantly." (PMID 20499351, 2010).
hypophosphatemia (continued). "Intact FGF-23 contributes to the hypophosphatemia observed in the first month after transplantation, but after the first 6 months possible causes are persistent secondary hyperparathyroidism, tubular damage, and/or immunosuppressive drugs." (PMID 20107581, 2009). "Patients that developed hypophosphatemia tended to have higher pre- and posttransplantation iPTH levels as well as higher pretransplantation FGF-23 levels." (PMID 20107581, 2009). "As a result disorders of FGF-23 excess are characterized by hypophosphatemia with increased renal phosphate wasting and inappropriately low calcitriol levels for the degree of hypophosphatemia." (PMID 20107581, 2009). "Recently, FGF-23 has been suggested to be responsible for the hypophosphatemia and inappropriately low calcitriol levels observed after renal transplantation." (PMID 20107581, 2009). "There was a tendency toward higher pretransplantation FGF-23 levels in patients that developed hypophosphatemia (451 ± 177 versus 302 ± 118 pg/mL, P = .147)." (PMID 20107581, 2009). "The participant was an 18-year-old woman with CSHS and FGF23-mediated hypophosphatemia." (PMID 41907689, 2026). "Laboratory evaluation revealed severe hypophosphatemia and elevated FGF23 levels." (PMID 42077462, 2026). "Laboratory evaluation demonstrated profound hypophosphatemia (1.6 mg/dL), markedly elevated FGF23 levels (455 RU/mL), and renal phosphate wasting (tubular reabsorption of phosphate at 35%, tubular maximum phosphate reabsorption per glomerular filtration rate (TmP/GFR) at 1.04 mg/dL)." (PMID 41737823, 2026). "Tumor-induced osteomalacia (TIO) is a rare paraneoplastic syndrome characterized by fibroblast growth factor-23 (FGF-23)-secreting mesenchymal tumors that cause renal phosphate wasting, hypophosphatemia, and osteomalacia, leading to debilitating musculoskeletal symptoms." (PMID 40951211, 2025). "TIO is clinically characterized by hypophosphatemia due to excessive production of FGF23 by PMTs." (PMID 41227266, 2025). "The efficacy of burosumab in XLH or FGF23-mediated hypophosphatemia with PHEX PV is well-published." (PMID 41445556, 2025). "The use of burosumab may be clinically supported in patients with persistent FGF23-mediated hypophosphatemia who necessitate recurrent exposure to intravenous iron formulations and are unable to be effectively managed with conventional therapy." (PMID 41445556, 2025). "Evaluation of the etiology is crucial and requires an algorithmic approach to determine whether hypophosphatemia is renally-mediated, FGF23-mediated, acquired or inherited." (PMID 41445556, 2025). "The next step is to consider acquired forms of FGF23-mediated hypophosphatemia such as tumor induced osteomalacia (TIO), which should be suspected in patients manifesting after the age of two years, and those presenting with severe bone pain and a brief history of symptoms." (PMID 40295317, 2025). "Burosumab significantly improves serum phosphate and fracture healing in XLH and may effectively treat other forms of FGF23-mediated hypophosphatemia." (PMID 41445556, 2025). "The resulting hypophosphatemia produces a reduction in serum levels of FGF23." (PMID 40943461, 2025). "Burosumab, an antibody targeting FGF23, improves hypophosphatemia and clinical outcomes." (PMID 40323576, 2025). "Here, we describe the case of a 69-year-old woman who presented with persistent hypophosphatemia, renal phosphate wasting, and elevated intact FGF-23 levels despite a normal C-terminal assay, ultimately managed successfully with burosumab in the absence of tumor localization." (PMID 40951211, 2025). "FGF23-mediated hypophosphatemia in TIO may be confused with hyperparathyroidism, renal tubulopathies, malabsorption, drug toxicity, or transcellular shifts." (PMID 39755803, 2025).